BRAF (B-Raf proto-oncogene, serine/threonine kinase)
Diseases named in the same sentence as BRAF in open-access papers (continued):
Sharing a sentence is not in itself a finding about the gene and the disease.
melanoma (continued). "The RAF-MEK-ERK pathway drives several features of oncogenic transformation, and BRAF is an oncogene in its own right that is frequently mutated in melanoma, colorectal cancer, and lung cancer, amongst others." (PMID 33920182, 2021). "As RICTOR overexpression in the TCGA dataset was correlated with the overexpression of BRAF, we focused our study on BRAF-mutated melanoma." (PMID 34680615, 2021). "BRAF mutations are found in about 40–60% of melanomas, with about 80% occurring as a V600E mutation, 5–30% as V600K mutations, and the rest other rare mutations." (PMID 34537078, 2021). "Approximately 50% of melanomas harbour BRAF mutations, whereas NRAS and KIT mutations are found in approximately 20%, and 2–3% of cases, respectively." (PMID 33530579, 2021). "In melanoma, driver mutations in BRAF were associated with mutational enrichment in CTCF binding sites (interaction P = 0.022)." (PMID 33941236, 2021). "We next examined that survival curves of melanoma patients from the TCGA data set for patients with a BRAF mutation along with high or low levels of INSR or IGF1R." (PMID 34831014, 2021). "In our cohort of patients with BRAF-wt melanoma, 22 out of 45 (49%) patients—with known NRAS mutation status—had a NRAS mutation." (PMID 33915880, 2021). "Yapeng Su integrated single-cell flow cytometry with theoretical investigation to study the cell-state transition dynamics associated with BRAF inhibitor drug resistance in BRAF-mutant melanoma cell." (PMID 35083160, 2021). "The BRAFV600E mutation site is directly adjacent to several dipyrimidines, and BRAF tandem mutations in melanoma are relatively common." (PMID 34066966, 2021). "In melanomas with the BRAF (V600E) mutation, the effective rate of using the RAF inhibitor verofinib is more than 50%." (PMID 34249669, 2021). "About 45% of melanomas, displaying wt BRAF and NRAS proteins, show mutation of the Neurofibromin 1 (NF1) oncosuppressor gene and loss of its control on Mitogen-Activated Protein Kinase (MAPK) activation." (PMID 34207514, 2021). "BCL2A1 expression is associated with more dismal clinical responses to BRAF inhibitors in melanoma patients." (PMID 34063141, 2021). "In fact, ELAVL1 knockdown led to suppression of the proliferation of melanoma cells with mutated BRAF (V600E), which is consistent with our results that ELAVL1 is a sensitive SP for mutated BRAF." (PMID 34681774, 2021). "With the emergence of high-throughput genomic technologies, several commonly mutated genes that play a central role in melanoma tumorigenesis and metastasis, such as BRAF, NRAS, and NF1, were identified." (PMID 33564068, 2021). "BRAF mutations, which are often present in more than half of melanoma patients, are treated with selective MAPK inhibitors." (PMID 33804114, 2021). "Considering the high frequency of hTERT promoter mutations, BRAF mutations, and copy number amplification of the hTERT gene in melanoma, patients with this cancer are more likely to achieve benefit from vaccination." (PMID 34290704, 2021). "In this study, BRAF/MEK inhibitors seemed to be effective against melanoma cells with various mutations in V600 and K601 residues of BRAF." (PMID 33731038, 2021). "BRAF is the most common gene mutated in malignant melanoma, and predominately it is a missense mutation of codon 600 in the kinase domain." (PMID 34066966, 2021). "The patients enrolled had BRAF V600 mutation-positive unresectable stage III or IV melanoma, and had received up to one previous round of systemic therapy for advanced disease; therefore, this population was not heavily pretreated." (PMID 34885172, 2021). "BRAFi/MEKi therapy is related to a high pathological response rate in borderline resectable stage III and IV BRAF-mutated melanoma patients." (PMID 35008274, 2021).
melanoma (continued). "A biopsy at that time revealed an epithelioid neoplasm with morphology and phenotype highly suggestive of melanoma that was positive for the BRAF V600E mutation." (PMID 33810799, 2021). "Testing of BRAF V600 mutation is now recommended in stage III and IV melanoma, since the presence of the mutation represents an ideal target, allowing the use of BRAF-inhibitors (BRAF-i), in both the adjuvant and the metastatic setting." (PMID 35008245, 2021). "Treatment of BRAF mutated melanoma with BRAF targeted therapies inhibits glucose uptake in preclinical models and patients." (PMID 34830962, 2021). "The release of HGF leading to HGFR activation was associated with resistance to BRAF inhibition in melanoma." (PMID 33918490, 2021). "In melanoma, PTEN is often mutated/deleted, and its loss of function is present and concomitant with BRAF mutations in about 44% of melanomas." (PMID 33917181, 2021). "It was also indicated that BRAF V600E-mutated melanoma cells exposed to acidosis exhibited vemurafenib resistance, even though phosphorylated ERK was suppressed." (PMID 33918883, 2021). "We cultured two melanoma cell lines with the BRAF V600E mutation, A375 and SK-MEL-28 specifically, for 8‒47 days on CDRA chips with a concentration gradient of vemurafenib." (PMID 33840166, 2021). "BRAF mutations have initially been described in malignant melanoma with 40–60% of tumors harboring an activating BRAF V600E mutation." (PMID 33671873, 2021). "Monomethyl auristatin E, a cytotoxic part of NECTIN4-targeted antibody–drug conjugate, was effective for BRAF-mutated or BRAFi-resistant melanoma cells." (PMID 33478111, 2021). "It was found that the presence of CD8+ T cell infiltration and PD-L1 immune cells at baseline is independently associated with better DFS in patients with fully resected, stage IIC-IIIC BRAF V600-mutated melanoma." (PMID 33925387, 2021). "In melanoma, widely distributed mutations in BRAF and NRAS genes make most of the technologies suitable for analysis." (PMID 34575876, 2021). "To avoid bias in this analysis, we selected melanoma samples harboring a mutation in the V600 BRAF codon (n = 17), as all the melanoma cell lines in our previous analysis also carried this mutation." (PMID 33670365, 2021). "Activating BRAF mutations present in 40–60% of melanoma patients induce aberrant activation of MAPK signaling, causing uncontrolled cellular growth." (PMID 34068792, 2021). "Not only is BRAF the most common gene mutated in melanoma, but mutations in the kinase domain occur in over 60% of malignant melanomas." (PMID 34066966, 2021). "Downregulation of BANCR in BRAF-mutated melanoma cell lines alters the expression of 88 genes, and most of the repressed genes have been involved in melanoma motility." (PMID 34638331, 2021). "In this setting, resistance to BRAFi in BRAF-mutant melanoma was associated with decreased FASN expression." (PMID 34068792, 2021). "Alternatively, the development of melanoma in the absence of accumulated UVR in occasionally exposed anatomical sites remains intriguing, and here we have shown how these nevogenic melanomas were associated with BRAF mutations." (PMID 34680367, 2021). "A small proportion, about 1-5% of melanoma patients, harbor mutations at codon K601 in exon 15 of the BRAF gene (BRAF-K601E), the third most common type of BRAF mutation, resulting in a single amino acid change from lysine (K) to glutamic acid (E)." (PMID 34123788, 2021). "Between 40–60% of melanoma tumors possess a mutation in the BRAF gene, resulting in oncogenic proliferation mediated by activation of the mitogen-activated protein kinase (MAPK) pathway." (PMID 34679325, 2021). "As a control, we used two lung cancer-derived cell lines, A549 (homozygous KRAS G12S mutation; KRAS non-addicted) and H358 (heterozygous KRAS G12C mutation; KRAS-addicted), and melanoma-derived cell line, A375 (homozygous BRAF V600E mutation; BRAF-addicted)." (PMID 33793658, 2021).
melanoma (continued). "In a considerable fraction of human melanomas, a combination of BRAF and PTEN mutations has been detected resulting in parallel hyper-activation of the MAPK and PI3K pathways." (PMID 34576054, 2021). "BRAF mutations have been utilized as predictors of response to targeted therapies in melanoma and colorectal cancer." (PMID 33448107, 2021). "Melanoma is currently treated with targeted therapy against mutations in the serine/threonine-protein kinase B-Raf (BRAF) or mitogen-activated protein kinase (MEK), which leads to tumor regression in up to 90% of patients." (PMID 33578808, 2021). "Approximately 20% of patients with BRAF V600E mutation melanoma had intrinsic resistance to BRAF inhibition." (PMID 34136385, 2021). "In melanoma, a French institutional cohort of Stage III melanoma patients of which 40% had confirmed BRAF+ mutational status showed BRAF mutant patients had significantly worse overall survival and distant metastasis-free survival." (PMID 34537078, 2021). "One neoadjuvant trial using dabrafenib, trametinib and/or pembrolizumab has shown that these treatments are well tolerated and demonstrate efficacy in treating BRAF-mutated stage III melanoma." (PMID 33807778, 2021). "In the COMBI-AD trial, patients with stage III melanoma and BRAF V600E or V600K mutations were randomized to receive 12 months oral dabrafenib plus trametinib or two matched placebos without radiation." (PMID 34537078, 2021). "BRAF mutations have been identified as driver mutations in glioma subsets and extracranial cancers, including melanoma which has a high propensity to metastasize to the brain." (PMID 33799709, 2021). "MAPK/ERK pathway mutations enhance proliferation, survival, and spread of melanoma cells, and thus, patients carrying the mutation are eligible for treatment with BRAF and MEK inhibitors." (PMID 33925915, 2021). "For the treatment of BRAF-mutated melanoma, various combination therapy regimens of a BRAF inhibitor plus MEK inhibitor, such as vemurafenib plus cobimetinib, encorafenib plus binimetinib, and dabrafenib plus trametinib, have been approved." (PMID 33807122, 2021). "Certain clinical features have been identified in BRAF-mutated melanomas (primary lesions located on the trunk, diagnosed in patients <50, visibly pigmented tumors and, at times, with ulceration or specific dermatoscopic features)." (PMID 34068774, 2021). "Targeting MAPK pathway using a combination of BRAF and MEK inhibitors is an efficient strategy to treat melanoma harboring BRAF-mutation." (PMID 34304249, 2021). "Certainly, effective diagnostic markers in the treatment of BRAF/NRAS-mutant melanoma are important in the development of a targeted therapy against advanced metastatic melanoma." (PMID 33723350, 2021). "In relation to primary melanoma, NRAS mutations have been associated with thicker lesions, higher mitotic rates, nodular primary subtype, and nodal relapse compared to BRAF-mutated and wild-type melanoma." (PMID 33530579, 2021). "The expression of BRAF‐V600E triggers oncogene‐induced senescence in normal cells and is implicated in the development of several cancers including melanoma." (PMID 34355491, 2021). "BRAF inhibitors have been shown to significantly lengthen PFS and OS in patients with melanoma harboring BRAF V600 mutations (V600E and V600K)." (PMID 34571863, 2021). "We found that the nevogenic melanomas had a restricted set of mutations, with the prominently mutated gene being BRAF." (PMID 34680367, 2021). "In line with published results, we observe BRAF mutations in 12% (25/201) of studied mucosal melanomas with V600E and variants detected in 72% and 28%, respectively." (PMID 34571863, 2021). "This missense mutation was first described in 2 prior reviews of BRAF mutations where it was identified in cases of non-small cell lung cancer and melanoma." (PMID 34965294, 2021).
melanoma (continued). "Blue-gray peppering and white scar-like areas, dermoscopic features related to histological regression, were also more frequently found in BRAF-mutated melanomas than in wild-type lesions (P = .044)." (PMID 33954019, 2021). "As is usually observed in cancers, gene mutations have been found in melanoma, such as in BRAF, KIT, NF, NRAS, and PTEN." (PMID 33478111, 2021). "Taken together, SIJ1777 turned out to be highly effective on melanoma cells harboring BRAF class II/III mutations as well as the BRAF class I mutation." (PMID 33917428, 2021). "The BRAF oncogene has emerged as a critical regulator of these processes in melanoma cells, underlying the importance of metabolic rewiring in the pathogenesis and treatment of metastatic melanoma." (PMID 34073463, 2021). "The higher mutation frequencies were mainly related to BRAF V600E mutations in thyroid cancer (61.8%) and melanoma (43.6%) and IDH1 R132H mutations in low-grade glioma (70.1%)." (PMID 33556087, 2021). "About 10–15% of melanomas harbor the BRAF mutation along with MITF amplification, suggesting that additional mechanisms are involved in ERK-dependent degradation of MITF." (PMID 34571969, 2021). "The network defined by phosphatidylinositol-3-kinase (PI3K), AKT, and mammalian target of rapamycin (mTOR) plays a major role in melanoma oncogenesis and has been implicated in BRAF inhibitor resistance." (PMID 34680615, 2021). "This article presents a summary of the ERG report for the STA of encorafenib with binimetinib (Enco + Bini) as a treatment for patients with advanced (unresectable or metastatic) BRAF V600 mutation-positive melanoma." (PMID 32291725, 2021). "NECTIN4-targeted therapy with ADCs, such as enfortumab vedotin, is a potential candidate for treating melanoma with BRAF-mutation and BRAFi-resistant melanomas, and its efficacy needs to be assessed in future research." (PMID 33478111, 2021). "The study partitioned melanoma tumors (both primary and metastatic) based on the pattern of the most prevalent mutated genes into four subtypes: BRAF, NRAS, NF1, and WT." (PMID 33564068, 2021). "We also tested the three-drug combination identified in our NF1/PTEN-mutant melanoma model in BRAF-mutant melanomas with PTEN mutations, because BRAF activation by mutation is more prevalent than biallelic inactivating mutations of NF1." (PMID 34331013, 2021). "As the BRAF V600E mutation has been found in over 50% of malignant melanomas, BRAF inhibitors, e.g., vemurafenib, are the most common form of therapeutics administered for melanoma treatment." (PMID 34822435, 2021). "BRAF itself is the main oncogenic driver in many different types of cancers: mutations have been identified in 45–50% of melanomas, 45–50% of thyroid cancers, 8–10% of colorectal cancers, and 1–5% of NSCLCs." (PMID 35155453, 2021). "Escalating doses of HSP90 inhibitors in combination with a BRAF inhibitor (vemurafenib) was shown to increase the overall survival of BRAF V600E-mutated melanoma patients." (PMID 33451095, 2021). "Our results indicate a treatment combination of VERU-111 and Vem holds a great promise to overcome Vem-resistance for melanoma patients harboring BRAF (V600E) mutation." (PMID 33841154, 2021). "The five-year analysis of adjuvant dabrafenib with trametinib in stage III melanoma with BRAF V600 mutations was presented in the COMBI-AD trial." (PMID 34804979, 2021). "In fact, constitutive activating mutations in BRAF are the most common oncogenic mutations, present in 40–60% of all melanoma cases." (PMID 34066966, 2021). "In order to confirm these in silico findings we performed qRT-PCR of BRAF mutated, treatment sensitive melanoma cell lines (A375, WM9, WM35 and WM902B) and found that miR-129-5p expression was increased after Vemurafenib treatment." (PMID 34063443, 2021).
melanoma (continued). "In melanoma, BRAF mutation occurs in 45–50% causes, specifically through mutations at the V600 codon." (PMID 34441278, 2021). "Approximately 60% of adult melanoma patients have identifiable oncogenic mutations in the BRAF gene, whilst another 20% have oncogenic NRAS mutations." (PMID 33996584, 2021). "CH6868398 displayed in vivo efficacy in a melanoma xenograft model, and combinatory treatment with PLX4720 BRAFi therapy induced apoptosis in BRAF-mutated melanoma cells." (PMID 33807778, 2021). "Genetic analysis of melanoma has allowed us to identify gene mutation in metastatic melanoma, and it was found that 50% of metastatic melanoma patients have BRAF mutation." (PMID 34371697, 2021). "In line with the previously observed differential response to BRAF inhibitors of BRAF V600E mutated melanoma and mCRC, the activity of AMG510 in KRAS G12C mutated CRC is substantially lower than in non-small cell lung cancer (NSCLC)." (PMID 34572729, 2021). "Three MEK inhibitors, including trametinib (GSK1120212), cobimetinib (XL518), and binimetinib (MEK162), are approved in combination with BRAF inhibitors for the treatment of patients with advanced melanoma harboring BRAF mutations (V600E or V600K)." (PMID 34607583, 2021). "Taken together, our six GNF-7 derivatives exhibit highly potent activities against melanoma cells harboring class I/II/III BRAF mutations compared with vemurafenib as well as PLX8394." (PMID 33917428, 2021). "The combination of dabrafenib and trametinib is a well-established treatment for BRAF-mutated melanoma." (PMID 34590600, 2021). "An example of such epigenetic heterogeneity is observed in BRAF-mutated melanomas, causing fractional responses to Braf/Mek-targeted therapies." (PMID 33750776, 2021). "Pathological associations exist between melanoma and TC, and this is stirring up interest in understanding mechanisms common to both cancers and how resistance to BRAF inhibitors treatment has common mechanisms of survival." (PMID 33578751, 2021). "During the same period as the development of the ICIs, targeted agents were also examined in patients with advanced melanoma harboring BRAF V600 mutations." (PMID 34677256, 2021). "This is reflected in mouse models, where melanocyte-specific activation of BRAF or NRAS is insufficient to generate melanomas but can do so when combined with loss of INK4a by mutation or its silencing by activated β-catenin." (PMID 34819350, 2021). "One of the most common mutations is the BRAF gene, whose inhibition showed a beneficial antitumor reaction against melanoma." (PMID 34069297, 2021). "Approximately, 60% of melanoma tumors harbor a BRAF mutation, most often BRAFV600E, which leads to hyperactivation of the mitogen-activated protein kinase (MAPK) pathway." (PMID 33438577, 2021). "Patients with BRAF-mutated melanoma metastases had enhanced eNAMPT levels in plasma as compared to patients without them and to healthy controls." (PMID 34068679, 2021). "BRAF is a paralog of CRAF (47% sequence identity) that is highly mutated in malignancies such as melanoma, thyroid carcinoma, colorectal cancer, and hairy cell leukemia, as well as the rare disease non–Langerhans cell histiocytosis." (PMID 33410398, 2021). "Targeted therapy can be used in patients with advanced melanoma with activated mutations in BRAF, which is a constituent of the mitogen-activated protein kinase (MAPK) pathway." (PMID 34201096, 2021). "In advanced melanoma, BRAF mutation testing is critical in predicting treatment response with targeted therapy (i.e., BRAF/MEK inhibitors)." (PMID 34068774, 2021). "We established eleven new melanoma primary cultures from metastatic lesions harboring different oncogenic BRAF and NRAS driver mutations, all explanted in both Ham’s F10 culture medium with 10 or 100 μM tyrosine." (PMID 34869032, 2021). "Melanomas harbor BRAF mutations (BRAF+) in 40–50% of cases, the majority of which are on the V600E residue." (PMID 34537078, 2021).